GOLPH3 (golgi phosphoprotein 3)
Diseases named in the same sentence as GOLPH3 in open-access papers (continued):
Sharing a sentence is not in itself a finding about the gene and the disease.
glioma (continued). "Likewise, we have previously shown that the knockdown of GOLPH3 in T98G cells also results in disrupted cell migration and invasion, which is also in agreement with what has been found in other glioma cell lines." (PMID 33238647, 2020). "Beyond invasiveness, also cell growth in gliomas is deeply influenced by GOLPH3." (PMID 32023813, 2020). "However, there is a negative correlation between tumor suppressor gene NDRG1 expression and GOLPH3 expression in glioma samples." (PMID 33015040, 2020). "This suggests that miR-299-5p regulates GOLPH3 expression (downregulation) via the MAPK/ERK pathway activation and indicates that also this small RNA may be used for depleting GOLPH3 in glioma therapy." (PMID 32023813, 2020). "The downregulation of GOLPH3 has been investigated also in other reports, and it has been demonstrated that depletion of this oncoprotein in human U251 and U87 glioma cell lines leads to the reduction of glioma cell migration and invasion." (PMID 32023813, 2020). "Therefore, our findings indicate that GOLPH3 enhances the tumour suppression effect of gefitinib on primary glioma cells." (PMID 31094020, 2019). "Nevertheless, clinicopathological data shows that in more than a dozen kinds of cancer, including gliomas, GOLPH3 could be found overexpressed, which correlates with poor prognosis." (PMID 30779783, 2019). "It will be very interesting to further explore whether GOLPH3 high glioma patients will be more sensitive to anti‐EGFR therapy and provide ideas for developing new possible treatments for individual glioma patients." (PMID 31094020, 2019). "Our results demonstrate that GOLPH3 increases the sensitivity of glioma cells to gefitinib." (PMID 31094020, 2019). "In the current study, we examine whether GOLPH3 affects the response of glioma cells to gefitinib, an EGFR selective inhibitor." (PMID 31094020, 2019). "In addition, primary glioma cells with higher GOLPH3 level exhibited stronger proliferation behaviour." (PMID 31094020, 2019). "Furthermore, our results also indicate that the promotion effect of GOLPH3 on glioma proliferation is mainly through enhancing the function of EGFR related pathways." (PMID 31094020, 2019). "The effect of GOLPH3 on enhancing migration and invasion of glioma cells could be abolished by either treatment with the mTOR inhibitor INK128 or by YB-1 knockdown." (PMID 28983350, 2015). "In glioma cells, the function of GOLPH3 requires mTOR and its effector YB-1." (PMID 28983350, 2015). "Furthermore GOLPH3 promotes the migratory and invasive behavior of glioma cells in vitro and this effect is abolished by either treatment with the mTOR inhibitor INK128 or by YB1 knockdown." (PMID 25691054, 2015). "However, the relationship between GOLPH3 and NF-κB in glioma cells is still unclear." (PMID 39944595, 2025). "Furthermore, in vivo studies demonstrated the higher ability of angiopep-2-modified GOLPH3-siRNA-liposomes to accumulate in the brain and effectively inhibit glioma growth in comparison with free GOLPH3-siRNA, suggesting the potential of this liposomal formulation for glioblastoma treatment." (PMID 35456655, 2022). "Likewise, human glioma cell lines such as A172, U87, U118, U251, and T98G cells overexpress GOLPH3." (PMID 33238647, 2020). "Importantly, the knockdown of GOLPH3 expression in the human glioma cell lines A172, U87, U118, and U251 promotes the endocytosis and downregulation of EGFR, emphasizing the putative role that GOLPH3 might have in regulating the function of this receptor." (PMID 33238647, 2020). "Furthermore, GOLPH3 also increased the sensitivity of primary glioma cell to gefitinib." (PMID 31094020, 2019). "Similarly, GOLPH3 has been considered as a novel oncogene involved in the development of cancer of the lung, ovary, breast, colon and prostate, as well as melanoma, rhabdomyosarcoma, and glioma." (PMID 28983350, 2015). "Thus, GOLPH3 may represent a promising therapeutic target for glioma treatment." (PMID 39944595, 2025).
glioma (continued). "In our experimental study, we first found that GOLPH3 affects glioma cell apoptosis and the JNK signaling pathway was either directly or indirectly regulated by GOLPH3 in glioma cells." (PMID 39944595, 2025). "Golgi phosphoprotein 3 (GOLPH3) is a gene product of the 5p13 gene, which has been correlated with glioma progression and shorter survival time and serves as a useful prognostic marker." (PMID 39457052, 2024). "When GOLPH3 was down-regulated, it resulted in a substantial reduction in the levels of YBX1 and mTOR activity, which are both crucial for glioma cell migration and invasion." (PMID 38255791, 2024). "The in vivo silencing of GOLPH3, in a combinatorial anti-tumor therapy, by using GOLPH3 siRNA and Gefitinib both conjugated to nanoparticles, inhibited EGFR signalling and glioma growth in the mouse model." (PMID 35465326, 2022). "Examined by EGFR immunofluorescence, we found that, either in the U251 or in the primary cultured glioma cells, the EGFR protein levels increased and accumulated at the cell membrane after GOLPH3 over‐expression." (PMID 31094020, 2019). "The expression of GOLPH3 and EGFR in glioma cells was detected by immunofluorescence and immunoblotting." (PMID 31094020, 2019). "We successfully cultured and identified several strains of primary glioma cells, which expressed higher GFAP, the molecular marker of gliomas, and higher GOLPH3 in the perinuclear region." (PMID 31094020, 2019). "In addition, we found significant upregulation of GOLPH3 mRNA levels in gliomas through analysis of TCGA and CGGA databases and patients with high levels of GOLPH3 expression have a poorer prognosis." (PMID 39944595, 2025). "A similar nanoparticle-mediated approach was used by Ye and co-workers, who co-delivered GOLPH3 siRNA and gefitinib (Ge, an anti-EGFR drug) in vitro (U87 and T98G glioma cell lines) and in vivo (BALB/c nude mice), obtaining growth inhibition and apoptosis induction." (PMID 32023813, 2020). "As said above, GOLPH3 interacts with the VPS35 retromer protein and Wnt/β-catenin, and consequently, Wntless (Wls, the chaperone protein of Wnt secretion) are important in glioma etiology." (PMID 32023813, 2020). "GOLPH3 knockdown increases NDRG1 and triggers apoptosis in glioma cells." (PMID 33015040, 2020). "Our findings provide foundation for further exploring whether the glioma patients with high GOLPH3 expression are more sensitive to anti‐EGFR therapy in clinic and develop possible treatment modalities for gliomas." (PMID 31094020, 2019). "Thereafter, the proliferation of GOLPH3 over‐expression U251 and U87 glioma cells, with or without gefitinib treatment, was detected by CCK8 and colony formation assay, respectively." (PMID 31094020, 2019). "Our study provides foundation for further exploring whether GOLPH3 high gliomas will be more sensitive to anti‐EGFR therapy in clinic and give ideas for developing new possible treatments for individual glioma patients." (PMID 31094020, 2019). "Recently, Golgi phosphoprotein 3 (GOLPH3) has been demonstrated as a novel oncogene involved in the development of cancer of the lung, ovary, breast, colon and prostate, as well as melanoma, rhabdomyosarcoma, and glioma." (PMID 23056210, 2012). "Several studies have reported that GOLPH3 promotes autophagy in glioma cells via PHB2 but not PHB1." (PMID 40168274, 2025).
colorectal cancer (17 papers, 2014 to 2025). A primary or metastatic malignant neoplasm that affects the colon or rectum. "Zhang and coauthors associated GOLPH3 protein to miR-3150b-3p function in colorectal cancer (CRC) cells." (PMID 32023813, 2020). "Furthermore, our investigation into the colorectal cancer microenvironment and genomic mutation signature underscored the oncogenic potential of GOLPH3, exacerbated by BPA exposure." (PMID 38828452, 2024). "Golgi Phosphoprotein 3 (GOLPH3) has been implicated in the development of colorectal cancer (CRC)." (PMID 34807928, 2021). "The results of this study demonstrated that the overall expression of GOLPH3 was found to be significantly higher than that of para‐carcinoma tissue, which signifies that the expression of GOLPH3 in colorectal carcinoma was negatively associated with cell apoptosis." (PMID 34807928, 2021). "Recent papers linked the overexpression of GOLPH3 to colorectal cancer (CRC)." (PMID 32023813, 2020). "Interestingly, it has been reported that high GOLPH3 expression is associated with favorable prognosis in colorectal cancer patients treated with 5-fluorouracil adjuvant chemotherapy." (PMID 29285241, 2017). "However, it is still unknown the association of GOLPH3 expression with the prognosis of colorectal cancer (CRC) patients who received 5-fluorouracil (5-FU)-based adjuvant chemotherapy." (PMID 24444035, 2014). "This study provides novel insights into the complex interactions between BPA exposure and GOLPH3 in the context of colorectal cancer, emphasizing the need for heightened awareness and measures to mitigate BPA exposure risks." (PMID 38828452, 2024). "Our findings demonstrated that BPA exposure significantly promoted the progression of colorectal cancer by upregulating GOLPH3, which in turn enhanced the malignant phenotype of colorectal cancer cells." (PMID 38828452, 2024). "To investigate the biological functions of GOLPH3 in colorectal cancer and its potential modulation by BPA exposure, we employed GSEA with the Hallmark gene set." (PMID 38828452, 2024). "The expression of GOLPH3 in cancer tissues and adjacent normal tissues and clinicopathological characteristics of patients with colorectal cancer." (PMID 34807928, 2021). "By conducting a random effects model (I2 = 0.0%, P = 0.453), the overall OR was observed to be 2.63 (95%CI = 1.96–3.52, P<0.001), These results indicate that GOLPH3 is highly expressed in colorectal cancer tissues." (PMID 34807928, 2021). "More precisely, an increased GOLPH3 expression correlates with an advantageous prognosis in patients treated with 5-FU and predicts a higher sensitivity towards 5-FU in colorectal cancer cells." (PMID 32424263, 2020). "The interaction between environmental endocrine-disrupting chemicals, such as Bisphenol A (BPA), and their influence on cancer progression, particularly regarding the GOLPH3 gene in colorectal cancer, remains unclear." (PMID 38828452, 2024). "In addition, we explored the potential underlying mechanism to verify whether LINC00641 can upregulate GOLPH3 expression through sponging miR-450b-5p, ultimately exerting an oncogene function in colorectal cancer." (PMID 35756081, 2022). "In colorectal cancer cells, for example, BPA induces the overexpression of GOLPH3, which promotes malignant behavior by activating the PI3K/AKT/mTOR cascade and ROS-driven HIF-1α/VEGF signaling, even under hypoxic conditions." (PMID 41440754, 2025). "Moreover, studies have demonstrated that downregulation of GOLPH3 expression can inhibit the proliferation, invasion and migration of colorectal carcinoma, indicating that GOLPH3 plays an important role in the development of CRC." (PMID 34807928, 2021). "In summary, we provided experimental evidence suggesting for the first time a novel role for miR-3135b in the protection of chemotherapy-induced Golgi fragmentation via GOLPH3/AKT1/mTOR axis and protective autophagy in colorectal cancer cells." (PMID 32601379, 2020).
colorectal cancer (continued). "Moreover, because increased expression of either RAB1A or RAB1B has been found in several types of cancer, including prostate cancer, hepatocellular carcinoma and colorectal carcinoma, it would be not surprising if their effects are synergistic with that of overexpressed GOLPH3." (PMID 32790781, 2020).
hepatocellular carcinoma (17 papers, 2015 to 2025). A malignant tumor that arises from hepatocytes. "Recent work has linked the up-regulation of GOLPH3 protein to activated NF-kB signaling in hepatocellular carcinoma." (PMID 32023813, 2020). "GOLPH3 is created by a gene residing on the 5p13 chromosome, a gene that is amplified in the context of different types of carcinomas, for example, hepatocellular cancer and gastric cancer." (PMID 37508488, 2023). "Interestingly, GOLPH3 is also elevated in lung, prostate, ovarian epithelial, hepatoma, and rectal cancers, implying that GOLPH3 plays a role in the occurrence or development of tumors and may have potential for use in cancer diagnosis." (PMID 29285241, 2017). "Golgi phosphoprotein 3 (GOLPH3) is frequently upregulated in hepatocellular carcinoma (HCC)." (PMID 39996775, 2025). "This study aimed at exploring whether GOLPH3 regulates angiogenesis and sorafenib resistance via exosomal mechanisms in hepatocellular carcinoma (HCC)." (PMID 35073936, 2022). "While little is known about the GOLPH3/PIP axis in MASLD progression, GOLPH3 has been shown to promote renal fibrosis and hepatocellular carcinoma, suggesting that the GOLPH3/PIP axis might have an uncharacterized role in hepatic fibrosis." (PMID 41032702, 2025). "An increasing number of papers has shown that GOLPH3 drives cancer in several other solid tumors such as Neuroblastoma (NB), Non-Small Cell Lung Cancer (NSLC), epithelial ovarian carcinoma, prostate cancer, gastric cancer, and hepatocellular carcinoma." (PMID 32023813, 2020).
prostate carcinoma (17 papers, 2012 to 2024). A carcinoma that arises from epithelial cells of the prostate gland. "In prostatic carcinoma, cytoplasmic GOLPH3 was associated with Gleason score, stage and androgen receptor (P = 0.034, P < 0.001, and P = 0.008 respectively)." (PMID 28983350, 2015). "In conclusion, an overexpression of GOLPH3 causes an abnormal differentiation of prostate cancer cells, thereby creating heterogeneity of tumor cells." (PMID 23006319, 2012). "In this study, it was discovered that the overexpression of GOLPH3 is associated with the transition of prostate cancer from hormone sensitive phase to hormone refractory phase." (PMID 23006319, 2012). "We also carried out retrospective follow-up analysis to explore the correlation between GOLPH3 expression and clinicopathologic factors associated with the prognosis of Chinese patients with prostate cancer." (PMID 23006319, 2012). "Furthermore, these data suggest the possibility of associating the over-expression of GOLPH3 with the progression of prostate cancer." (PMID 23006319, 2012). "In fact, determining the expression of GOLPH3 might also help in further elucidating the risk of progression of prostate cancer in patients." (PMID 23006319, 2012). "GOLPH3 has been identified as an oncoprotein and is significantly upregulated in prostate cancer, esophageal cancer, gastric cancer, ovarian cancer, and colon cancer." (PMID 38806777, 2024). "Number (percentage) of patients in groups differing in the percentage of GOLPH3 positive prostate cancer cells (“A” score in IRS scale) in the material from the prostate or metastatic lymph node, risk factors, and results of chi-square tests of independence." (PMID 37790749, 2023). "Further research is needed to understand the functional significance and potential clinical applications of GOLPH3 in prostate cancer." (PMID 37790749, 2023). "GOLPH3 is an oncogene that is known to be upregulated in breast cancer, esophageal cancer, glioma, prostate cancer and other cancers." (PMID 34807928, 2021). "Numerous studies have confirmed that the expression level of GOLPH3 protein in various solid tumor tissues, such as esophageal cancer, gastric cancer, lung cancer, liver cancer and prostate cancer, is significantly higher than that in normal tissues." (PMID 34807928, 2021). "For example, miR-186 suppressed cell proliferation by negatively targeting oncogene GOLPH3 in prostate cancer tissues." (PMID 33628370, 2021). "The critical golgi related gens, GOLPH2, GOLM1 and GP73, can also be the potential biomarkers in prostate cancer and liver cancer.GOLPH3 was also reported to be the potential biomarker in some kinds of cancers." (PMID 29534690, 2018). "High GOLPH3 and nuclear/cytoplasmic YB-1 expression correlated with poor prognosis in prostate cancer." (PMID 28983350, 2015). "But, we cannot decipher the correlation of GOLPH3 expression with cellular hyperproliferation and tumorigenesis, especially during the early stages of prostate cancer development." (PMID 23006319, 2012). "Using long serial analysis of gene expression, GOLPH3 was identified as a novel androgen-responsive gene in prostate cancer." (PMID 23056210, 2012). "It is interesting to note that 98 (40.66%) of 241 prostate cancer showed GOLPH3 moderate/intense expression." (PMID 23006319, 2012). "On the other hand, multivariate analysis indicated that GOLPH3 was a significantly independent prognostic factor of DFS (P = 0.027) in all prostate cancer patients." (PMID 23006319, 2012). "Number (percentage) of patients in groups differing in the intensity of staining in GOLPH3 positive prostate cancer cells (“B” score in IRS scale) in the material from the prostate or metastatic lymph node, risk factors, and results of chi-square tests of independence." (PMID 37790749, 2023). "Hsa-miR-133a-3p, miR-1-3p, GOLPH3 and JUP are functional drivers of PCa and may be their combination is a promising diagnostic biomarker panel for prostate cancer." (PMID 36387263, 2022).
prostate carcinoma (continued). "In prostate cancer, patients with high levels of GOLPH3 will have shorter survival time." (PMID 31921678, 2019). "Same is reasonable that to determine the changes of GOLPH3 expression may also facilitate to comprehensively understand the incidence of progression in patients with prostate cancer." (PMID 31921678, 2019). "In our previous works, it was revealed that overexpression of GOLPH3 promoted the progression of prostate cancer from hormone sensitive stage to hormone stage, and GOLPH3's potential as a novel biomarker and potential target for antagonizing castration resistant prostate cancer." (PMID 31921678, 2019). "Not only prostate cancer, but also GOLPH3 has been proved to be highly expressed in NSCLC tissues, indicating that GOLPH3 may be a useful diagnostic factor for NSCLC." (PMID 31921678, 2019). "Upregulation of GOLPH3 promotes proliferation of prostate cancer." (PMID 29534690, 2018). "Finally, Golgi phosphoprotein 3 (GOLPH3), a protein involved in Golgi-membrane integrity and mTOR amplification, is enriched in prostate cancer patients urinary exosomes as well." (PMID 26196085, 2015). "GOLPH3 expression is an important parameter used in the prognosis of prostate cancer patients." (PMID 23006319, 2012). "However, research studies have seldom studied the correlation between GOLPH3 expression and prognosis of Chinese patients with prostate cancer." (PMID 23006319, 2012). "On the other hand, over-expression of GOLPH3 could be correlated with the progression of prostate cancer from its hormone sensitive phase to hormone refractory phase." (PMID 23006319, 2012). "Therefore, we can conclude that GOLPH3 serves as a biomarker for predicting the severity of prostate cancer." (PMID 23006319, 2012). "All the 241 prostate cancer patients were examined to determine their GOLPH3 status." (PMID 23006319, 2012). "In this research study, we have discovered that GOLPH3 expression does not have any correlation with cellular hyperproliferation and tumorigenesis, particularly in the early stages of prostate cancer." (PMID 23006319, 2012). "Moreover, GOLPH3 may be of significant potential as predictive marker of DFS and OS in subjects with diagnosed prostate cancer." (PMID 31921678, 2019). "Furthermore, GOLPH3 might be a favorable prognostic factor of DFS and OS in patients diagnosed with prostate cancer." (PMID 23006319, 2012). "GOLPH3 might be an important prognostic factor of DFS and OS in patients with prostate cancer." (PMID 23006319, 2012).